KSR2 (kinase suppressor of ras 2)
Diseases named in the same sentence as KSR2 in open-access papers (continued):
Sharing a sentence is not in itself a finding about the gene and the disease.
Insulin resistance (11 papers, 2013 to 2024). Increased resistance towards insulin, that is, diminished effectiveness of insulin in reducing blood glucose levels. "Individuals carrying KSR2 mutations exhibit childhood hyperphagia, reduced basal metabolic rate, and severe insulin resistance." (PMID 24997067, 2014). "Clinical reports suggested that some KSR2 mutation carriers experienced marked weight loss in childhood when prescribed the antidiabetic drug metformin (for severe insulin resistance)." (PMID 24209692, 2013). "KSR2 is involved in multiple signaling pathways and plays a role in energy homeostasis and insulin resistance." (PMID 38267854, 2024). "In clinical studies, it has been found that patients who lose the function of KSR2 have severe insulin resistance." (PMID 37334291, 2023). "In addition, six loci were linked to insulin resistance, type 2 diabetes, or reduction in HbA1c levels in type 2 diabetes (APOB, HPR, TM6SF2, KSR2, JMJD1C, and SLCO1B1)." (PMID 38532495, 2024). "In our previous study 6-8, we found that insulin resistance contributes to multidrug resistance in HCC cells via activation of the ER stress, suggesting that KSR2 may be involved in therapy resistance in insulin resistant HCC." (PMID 32210717, 2020).
endometrial cancer (5 papers, 2020 to 2025). Primary or metastatic malignant neoplasm involving the endometrium (mucous membrane that lines the endometrial cavity). "Taken together, these data suggest that SF3B1 exerts its functions by generating mature splice variants and KSR2 is one such downstream effectors of SF3B1 function in endometrial cancers." (PMID 33040078, 2020). "The splicing factor SF3B1 promotes proliferation and invasion by regulating KSR2 RNA maturation in endometrial cancer cells." (PMID 39910288, 2025). "Related studies on RNA-binding proteins have found that the splicing factor SF3B1 accelerates the growth of endometrial cancer cells by controlling KSR2 RNA maturation." (PMID 35715407, 2022). "Subsequently, bioinformatics analysis showed KSR2 as a potential candidate for SF3B1-mediated functions in endometrial cancer." (PMID 33040078, 2020). "In summary, we report that SF3B1 plays an important role in endometrial cancer initiation and progression possibly through regulating KSR2 mRNA maturation." (PMID 33040078, 2020). "Since, Ras signaling is the primary mitogenic pathway of endometrial cancer, we decided to focus on KSR2, a Ras signaling promoting gene for subsequent studies." (PMID 33040078, 2020). "As expected, we found SF3B1 regulated the KSR2 expression in endometrial cancer cells both at transcript and protein levels." (PMID 33040078, 2020). "Furthermore, the suppression of SF3B1 has been shown to induce G2/M arrest in endometrial cancer cells and impede the maturation of KSR2 pre-mRNA5." (PMID 39910288, 2025). "For example, SF3B1 regulated KSR2 RNA maturation to promote endometrial cancer progression." (PMID 34966670, 2021). "Importantly, we found rescuing the KSR2 expression with SF3B1 knockdown partially restored the cell growth of endometrial cancer cells." (PMID 33040078, 2020). "Finally, we report that knockdown of SF3B1 alters mRNA maturation of the kinase suppressor of Ras gene KSR2 and KSR2 acts as a downstream mediator of SF3B1 function(s) in endometrial cancer." (PMID 33040078, 2020).
type 2 diabetes (5 papers, 2013 to 2024). "Two KSR2 mutation carriers were excluded a priori from studies due to a diagnosis of type 2 diabetes." (PMID 24209692, 2013).
glioma (3 papers, 2022 to 2024). A benign or malignant brain and spinal cord tumor that arises from glial cells (astrocytes, oligodendrocytes, ependymal cells). "Among five malignant tumor types, glioma and liver cancer had the highest expression of KSR2 based on data from the Human Protein Atlas." (PMID 35468812, 2022). "While only two genes including SLC12A5 and KSR2 exhibited lower accessibility of enhancer region in GBM and decreased level of expression in glioma tissue." (PMID 38685685, 2024).
melanoma (3 papers, 2020 to 2024). A malignant, usually aggressive tumor composed of atypical, neoplastic melanocytes. "Notably, KSR2 has also been linked to MAPK pathway reactivation and resistance to BRAF+MEK inhibition in melanoma cells, thus suggesting that the roles of KSR1 or KSR2 in modulating the response to KRAS/MAPK pathway inhibition may have been underestimated." (PMID 35313064, 2022). "For instance, in mutant melanoma with BRAF inhibitor treatment, Grp78 binds the scaffold protein KSR2 to form a multiprotein complex, which acts independently of the UPR to activate ERK and promote the phosphorylation of ATF4." (PMID 38378757, 2024).
Coronary artery disease (2 papers, 2022 to 2026). "Atherosclerosis, the pathological foundation of coronary artery disease, is closely linked to metabolic dysfunction, yet the functional role of KSR2 in this disease process remains unknown." (PMID 41424849, 2026). "Rationale: The single nucleotide polymorphism (SNP) rs11830157 within the scaffold protein kinase suppressor of Ras 2 (KSR2) locus is strongly associated with the incidence of coronary artery disease (CAD), yet its functional role remains undefined." (PMID 41424849, 2026). "Given that the pathological basis of coronary artery disease is atherosclerosis, we hypothesize that endothelial KSR2 may contribute to the progression of atherosclerosis." (PMID 41424849, 2026).
age-related macular degeneration (1 paper, 2021). Age-related loss of vision in the central portion of the retina (macula), secondary to retinal degeneration. "Utilizing PhenGenI, the gene found to be associated with PXF in our GWAS analysis was KSR2 rs895471, and the connector enhancer of this gene (CNKSR2) was found to be associated with age-related macular degeneration." (PMID 34299682, 2021).
atherosclerosis (1 paper, 2026). A disease characterized by the build-up of fatty material and calcium deposition in the arterial wall resulting in partial or complete occlusion of the arterial lumen. "In summary, our study identifies the CAD-associated SNP rs12822146 as being linked to KSR2 gene expression in endothelial cells, suggesting that endothelial KSR2 may play a significant role in the pathogenesis and progression of atherosclerosis." (PMID 41424849, 2026). "Taken together, these findings suggest that KSR2 mitigates the progression of atherosclerosis by suppressing endothelial inflammation and apoptosis." (PMID 41424849, 2026). "This is an intriguing finding because KSR2 not only regulates systemic metabolic parameters, such as lipid levels, but changes in lipid levels can further modulate KSR2 expression in endothelial cells, thereby influencing the development of atherosclerosis." (PMID 41424849, 2026). "Using multiple KSR2 gene-edited mouse models, we demonstrated that endothelial KSR2 protects against atherosclerosis by suppressing inflammation and apoptosis." (PMID 41424849, 2026). "In this study, we confirm that in an atherosclerosis model, endothelial KSR2 competes with CRBN to bind the N-terminal of AMPKα1, particularly at the K52 site." (PMID 41424849, 2026). "Given that endothelial inflammation and apoptosis play pivotal roles in the initiation and progression of atherosclerosis 26, we next investigated the effects of KSR2 on endothelial inflammation and apoptosis both in vivo and in vitro." (PMID 41424849, 2026). "Functional studies of KSR2 further confirmed its protective role against atherosclerosis in endothelial cells." (PMID 41424849, 2026). "To assess whether similar KSR2 expression patterns occur in murine atherosclerosis, we established a progressive atherosclerosis model in Apoe-/- mice through high-fat diet (HFD) feeding for 0, 4, 8, and 12 weeks." (PMID 41424849, 2026). "Next, we investigated whether endothelial KSR2 attenuates atherosclerosis via the AMPK signaling pathway both in vivo and in vitro." (PMID 41424849, 2026). "In this study, we elucidated the molecular mechanism by which KSR2 attenuates atherosclerosis." (PMID 41424849, 2026). "Collectively, these findings suggest that vascular KSR2—particularly within endothelial cells—may play a critical role in the pathogenesis and progression of atherosclerosis." (PMID 41424849, 2026). "To assess the role of KSR2 in atherosclerosis, we utilized global KSR2 knockout mice fed a high-fat diet ad libitum, pair-fed global KSR2 and Apoe (Apolipoprotein E) double knockout mice, and mice with endothelial-specific KSR2 overexpression mediated by AAV9-ICAM2." (PMID 41424849, 2026). "Therefore, we investigated whether the protective effect of endothelial KSR2 against atherosclerosis is mediated through glycolysis." (PMID 41424849, 2026). "However, it remains unclear whether KSR2 can influence the development of atherosclerosis through a cell-autonomous mechanism." (PMID 41424849, 2026). "To further investigate whether KSR2 contributes to atherosclerosis development in a cell-autonomous manner, we generated KSR2 knockout mice on an Apoe-/- background, then controlled the food intake of Apoe-/-KSR2-/- mice to match that of the Apoe-/- mice through pair feeding (PF)." (PMID 41424849, 2026). "To further investigate the role of endothelial KSR2 in atherosclerosis, we administered AAV9-ICAM2-KSR2 (AAV9-KSR2) via tail vein injection into Apoe-/- mice, resulting in endothelial-specific overexpression of KSR2." (PMID 41424849, 2026). "Specifically, KSR2 regulates endothelial glycolytic balance through activation of the AMPK signaling pathway, thereby inhibiting endothelial inflammation and apoptosis, which ultimately slows the progression of atherosclerosis." (PMID 41424849, 2026).
atherosclerosis (continued). "Using HFD ad libitum-fed KSR2−/− mice, HFD pair-fed Apoe−/−KSR2−/− mice and AAV9-KSR2 endothelium-specific overexpression models, we demonstrated that endothelial KSR2 regulates atherosclerosis progression independently of systemic lipid and glucose alterations." (PMID 41424849, 2026). "Moreover, knockdown of XBP1s led to a marked upregulation of KSR2 in endothelial cells, regardless of the presence of the atherosclerosis-related stimulus oxLDL, suggesting that XBP1s functions as a transcriptional repressor of KSR2." (PMID 41424849, 2026). "Furthermore, KSR2 activates the AMPK signaling pathway through a non-canonical mechanism in endothelial cells, thereby delaying the progression of atherosclerosis." (PMID 41424849, 2026).
cataract (1 paper, 2021). Partial or complete opacity of the crystalline lens of one or both eyes that decreases visual acuity and eventually results in blindness. "We found that KSR2 was nominally associated with PXF and 13 novel genes associated with cataracts at a significant genome-wide level." (PMID 34299682, 2021).
hearing loss (1 paper, 2024). "KSR1 is the dominant protein expressed rather than KSR2 which is one of the reasons this genetic mouse model is useful for studying the role of the MAPK pathway in hearing loss." (PMID 38548338, 2024).
hepatocellular carcinoma (1 paper, 2022). A malignant tumor that arises from hepatocytes. "In summary, the present study demonstrates that KSR2 regulates the proliferation and growth of hepatocellular carcinoma." (PMID 35468812, 2022). "Kinase suppressor of Ras 2 (KSR2) is a regulator of MAPK signaling that is overactivated in most hepatocellular carcinoma (HCC)." (PMID 35468812, 2022).
Infertility (1 paper, 2017). "For ABCG8 and KSR2, animal models provide further support as gene expression deficiency can cause infertility in females (ABCG8,) and males (KSR2,)." (PMID 28640878, 2017).
liver cancer (1 paper, 2022). An epithelial or non-epithelial malignant neoplasm that arises from the liver. "In these available data, high expression of KSR2 is the only meaningful risk factor (p < 0.05) for the occurrence of liver cancer." (PMID 35468812, 2022).
lung carcinoma (1 paper, 2026). "This study identifies kinase suppressor of Ras 2 (KSR2) as a driver of resistance to anti-PD-1 therapy in lung cancer." (PMID 42012646, 2026).
myeloid leukemia (1 paper, 2012). A clonal proliferation of myeloid cells and their precursors in the bone marrow, peripheral blood, and spleen. "For instance, in myeloid leukemia cells in culture 1,25-VD affects cell survival by upregulation of the AKT, and the KSR2 pathways." (PMID 22498490, 2012).
neuroblastoma (1 paper, 2022). Neuroblastoma (NB) is the most common solid, extracranial childhood tumor. "An additional study reported KSR2 facilitates the activation of AMPK, which is essential for nutrient metabolism, maximum glycolysis, and oxidative phosphorylation (OXPHOS) capacity of neuroblastoma cells." (PMID 35468812, 2022).
rectal adenocarcinoma (1 paper, 2025). "Ksr2methylation, which is linked to rectal adenocarcinoma survival, reveals the role of DNAmethylation in compacting DNA and silencing genes, contrasting alkylation effects.These findings underscore the vital epigenetic role of ksr2 in cellularfunction." (PMID 40062973, 2025).
tumor (13 papers, 2016 to 2026). "Key proteins associated with tumor development such as myocyte enhancer factor 2 (MEF2), kinase suppressor of ras 2 (KSR2), DAXX, c-Jun, and nuclear factor I (NFI), are known CaN substrates." (PMID 35163061, 2022). "KSR2 overexpression increased the tumor growth rate and KI67-positive cell numbers in both dimethyl sulphoxide (DMSO) and sorafenib-treated nude mice xenografts." (PMID 35468812, 2022). "More importantly, our investigation reveals that high expression levels of KSR2 and 14–3-3ζ are significantly correlated with tumor growth and serve as independent prognostic factors for the poor outcomes of HCC patients." (PMID 35468812, 2022). "Tumors derived from KSR2-knockdown cells were smaller and grew slower than those from the control cells, whereas overexpression of KSR2 increased tumor size and promoted tumor growth." (PMID 35468812, 2022). "To explore the relationship between KSR2 and tumor cell proliferation, we examined co-expression of KSR2 and the proliferating cell nuclear antigen (PCNA), human Ki67 (MKI67) protein, and histone deacetylase 1 (HDAC1)." (PMID 35468812, 2022). "Recent work reported that AMPK activity is required and necessary for kinase suppressor of Ras 2 (KSR2)-mediated transformation and anchorage-independent growth of tumor cells MIN6 and NG108-15." (PMID 27449088, 2016). "Notably amplified regions included the KSR2, CANT1, MSI2 and MAP2K4 genes, all of which have been implicated in tumour progression, cell signalling, or regulation of proliferation." (PMID 40813389, 2025). "Expression of each of these proliferative markers (PCNA, MKI67, and HDAC1) positively correlated with that of KSR2, indicating KSR2 may promote tumor proliferation." (PMID 35468812, 2022). "KSR2 overexpression also abrogated the effect of sorafenib treatment in our tumor-xenograft model." (PMID 35468812, 2022). "KSR2 was also reported as an activator to stimulate tumor cell transformation." (PMID 32210717, 2020). "In this study, we found that KSR2 was upregulated in HCC and promoted tumor cell proliferation through the MAPK pathway." (PMID 35468812, 2022). "To further verify that KSR2 promotes HCC, we examined expression of KSR2 in tissue microarrays that were created with tumor and adjacent normal liver tissues from 198 HCC patients who underwent radical resection from 2007 to 2017." (PMID 35468812, 2022). "Considering that KSR2 appears to act via the MAPK pathway, we tested the effects of KSR2 overexpression on tumor-cell sensitivity to sorafenib, a drug that blocks tumor growth and angiogenesis by targeting both the MAPK pathway and receptor tyrosine kinases." (PMID 35468812, 2022). "As predicted, the staining for KSR2, pThr172-AMPK, and AMPKα1, was increased in tumor sections from SANPs-siPraja2-treated mice, compared to controls." (PMID 35918402, 2022). "Functionally, we determined the effects of KSR2 on the proliferation, migration, and invasion of HCC cells through colony formation assays, scratch assays, transwell migration assays, and xenograft tumor models." (PMID 35468812, 2022). "Finally, KSR2 is an activator of ERK signaling, and its overexpression stimulates tumor cell transformation." (PMID 30987652, 2019). "We further confirmed with RT-qPCR that relative KSR2 expression did not increase in Ksr1-/- compared to Ksr1+/+ tumor samples, and so a compensatory role for KSR2 is less likely." (PMID 29596465, 2018).
cancer (11 papers, 2019 to 2026). A tumor composed of atypical neoplastic, often pleomorphic cells that invade other tissues. "Mechanistically, KSR2 functions as a central metabolic checkpoint, driving profound glucose metabolic reprogramming in cancer cells by enhancing glucose uptake, potentiating the Warburg effect, promoting lactate accumulation, and disrupting the tricarboxylic acid cycle." (PMID 42012646, 2026). "Trametinib derives its clinical anti-cancer efficacy from promoting the interaction of its primary targets MEK1/2 with KSR1/2, but has low affinity for KSR1 or KSR2 alone, meaning this interaction was missed during clinical development." (PMID 38049406, 2023). "At the single nucleotide polymorphism (SNP) mutation level and transcriptional level, we found that MAP4, YWHAG, KSR2, SPAG9, and CEP250 gene-related loci are different in cancer and paracancer tissues, and MAP4, YWHAG, CEP135, and CEP250 differed significantly at the transcriptional level." (PMID 36705386, 2023). "The role of KSR2 in cancer has not been extensively explored." (PMID 35468812, 2022).
metabolic disorders (3 papers, 2013 to 2026). "Modulation of the intensity and duration of ERK signaling may be a mechanism by which KSR2 mutations are associated with metabolic disease." (PMID 24209692, 2013).
KSR2 also shares sentences with these, for which no sentence is quoted: diabetes (2 papers); dyslipidemia (2); -dependent (1); colorectal cancer (1); craniosynostosis (1); glioblastoma (1); Glucose intolerance (1); insomnia (1); ischemic stroke (1); leukemia (1); uveal melanoma (1).